RNU6-939P (RNA, U6 small nuclear 939, pseudogene)
Gene: Small nuclear RNA gene on chromosome 2 (37,331,770 to 37,331,876, reverse strand). Ensembl gene ENSG00000207364.
Homologues: Orthologues: chimpanzee U6 (100% identical). Paralogues in human: RNU6-43P (89% identical), RNU6-1124P (88% identical), RNU6-1216P (88% identical), RNU6-1243P (88% identical), RNU6-24P (88% identical), RNU6-454P (88% identical), RNU6-11P (87% identical), RNU6-19P (87% identical), RNU6-37P (87% identical), RNU6-49P (87% identical), RNU6-1099P (86% identical), RNU6-12P (86% identical), and 1290 more.